ISY1-RAB43 (ISY1-RAB43 readthrough)
Gene: Protein-coding gene on chromosome 3 (129,087,575 to 129,161,036, reverse strand). Ensembl gene ENSG00000261796.
Genetic constraint (gnomAD): Loss-of-function variants: 14 observed, 59.07 expected, observed/expected ratio (o/e) 0.24, 90% interval 0.16 to 0.37. The upper end of that interval is the gene's LOEUF score, 0.37, which puts it in group 1 of 6, group 1 being the genes least tolerant of losing a copy. Missense variants: 327 observed, 421.84 expected, observed/expected ratio (o/e) 0.78, 90% interval 0.71 to 0.85. Synonymous variants: 117 observed, 150.32 expected, observed/expected ratio (o/e) 0.78, 90% interval 0.67 to 0.91.